ALK (ALK receptor tyrosine kinase)
Diseases named in the same sentence as ALK in open-access papers (continued):
Sharing a sentence is not in itself a finding about the gene and the disease.
Histiocytosis (continued). "Several case reports and small case series on ALK-positive histiocytosis have been published in recent years." (PMID 40700600, 2025). "Herein, we present the case of a 6-month-old infant with mono-systemic, cutaneous ALK-positive histiocytosis harboring DCTN1::ALK fusion." (PMID 40361876, 2025). "Histiocytic neoplasms encompass a spectrum of disorders including JXG, ECD, RDD, ALK-positive histiocytosis, and histiocytic sarcoma, each with distinct clinical implications." (PMID 38963520, 2024). "The role of EML 4-ALK fusion in the pathogenesis, treatment, and prognosis of ALK-positive histiocytosis, especially in patients with isolated lung involvement, still needs to be further explored." (PMID 39867882, 2024). "Based on the findings in the literature, histiocytosis cases, especially those with neurological involvement, should be examined for ALK positivity or ALK alterations." (PMID 38339401, 2024). "ALK-positive histiocytosis exhibits positivity for ALK protein and ALK gene rearrangement, whereas RDD lacks these features." (PMID 38903706, 2024). "ALK-positive histiocytosis is characterized by rearrangements in the ALK gene, with the ALK::KIF5B fusion being more commonly detected." (PMID 38713245, 2024). "Conditions such as histiocytic sarcoma, Rosai-Dorfman disease, ALK-positive histiocytosis, ECD, and juvenile xanthogranuloma are neoplastic counterparts of macrophages." (PMID 38713245, 2024). "ALK-positive histiocytosis is an exceptionally rare neoplasm of histiocytes that predominantly involves the nervous system and can also affect the skin and other parts of the body." (PMID 38463230, 2024). "The multimodal imaging findings of ALK-positive histiocytosis exhibit distinct characteristics, familiarity with which will enhance radiologists’ expertise and facilitate accurate diagnosis of this disease." (PMID 38463230, 2024). "ALK-positive histiocytosis, a distinct entity first identified in 2008 in infants with liver and hematopoietic system involvement, is now known to have a broader clinical spectrum." (PMID 38963520, 2024). "ALK-positive histiocytosis is a relatively rare subtype of istiocytosis, which are rare disorders characterized by the accumulation of histiocytes in various tissues." (PMID 38713245, 2024). "The lung nodules were diagnosed as ALK-positive histiocytosis (APH) carrying an EML4::ALK gene fusion, which microscopically displayed a mixed morphology of foamy cells, spindle cells, and Touton’s giant cells." (PMID 39867882, 2024). "The patient was ultimately diagnosed as ALK-positive histiocytosis, accompanied by cauda equina and skin involvement." (PMID 38463230, 2024). "A recent study, which represents the largest series of ALK-altered histiocytosis cases to date, highlighted the frequent involvement of the nervous system in these conditions." (PMID 38339401, 2024). "This is the first reported case of malakoplakia with aberrant ALK expression, it should be differentiated from ALK-positive histiocytosis to avoid misdiagnosis." (PMID 37644531, 2023). "Histology and immunophenotype of the tumor overlaps with Erdheim–Chester disease, juvenile xanthogranuloma and ALK-positive histiocytosis." (PMID 36416966, 2023). "In contrast to peripheral eosinophilia, tissue eosinophilia is common in histiocytosis, particularly Langerhans cell histiocytosis (formerly called eosinophilic granuloma), Erdheim–Chester disease, and ALK-positive histiocytosis." (PMID 37274287, 2023). "Involvement of the central nervous system (CNS) has become the most common manifestation of ALK-positive histiocytosis." (PMID 36915094, 2023). "Anaplastic lymphoma kinase (ALK)-positive histiocytosis, a novel rare histiocytic proliferation, was first described in 2008; it occurs in early infancy with liver and hematopoietic involvement." (PMID 36915094, 2023). "KIF5B-ALK has emerged as the most frequent molecular alteration in ALK-positive histiocytosis (83%, 44/53)." (PMID 36915094, 2023).
Histiocytosis (continued). "Anaplastic lymphoma kinase (ALK)-positive histiocytosis, a novel systemic histiocytic proliferation in early infancy with hepatosplenomegaly and hematological abnormalities, was first described in 2008." (PMID 36915094, 2023). "In contrast, ALK-positive histiocytosis is more common in infants and young adults and is mainly composed of non-foamy histiocytes with irregularly folded nuclei and ALK translocations." (PMID 36915094, 2023). "After being diagnosed with ALK-positive histiocytosis, the patient received alectinib orally for 14 months." (PMID 36915094, 2023). "The most recently described, predominantly pediatric ALK-positive histiocytosis sometimes presents with isolated CNS involvement." (PMID 36416966, 2023). "Differential diagnosis of ALK-positive histiocytosis includes Erdheim-Chester disease (ECD), Langerhans cell histiocytosis (LCH), and Rosai-Dorfman disease (RDD)." (PMID 36915094, 2023). "Cyclin D1 overexpression has been reported in both Rosai–Dorfman disease and ALK-positive histiocytosis and is related to both MAPK/ERK and PI3K/AKT/mTOR pathway activation." (PMID 36416966, 2023). "In this study, we report the first case of synchronous bilateral breast involvement of ALK-positive histiocytosis on initial presentation in a 46-year-old Hispanic woman." (PMID 38093982, 2023). "ALK aberrations have also been described, albeit uncommonly, in rare hematologic disorders such as histiocytosis." (PMID 37773318, 2023). "The histiocytes in ALK-positive histiocytosis can assume variable appearances including large oval cells, foamy cells and spindle cells, some with multinucleation (including Touton giant cells) or emperipolesis." (PMID 35732831, 2022). "ALK-positive histiocytosis can occur in both children and adults, while pediatric cases are more likely to have a disseminated disease that primarily affects the liver, spleen, or bone marrow." (PMID 35359354, 2022). "Herein, we report a case of ALK-positive histiocytosis invading the central nervous system and lungs and the details of follow-up of tumor dynamic changes during treatment." (PMID 35359354, 2022). "Here, we report a rare case of intracranial disseminated ALK-positive histiocytosis in a child, mainly located in the suprasellar area, and discuss in detail the radiographic morphological changes occurring during chemotherapy and anti-ALK therapy." (PMID 35359354, 2022). "Once the diagnosis of ALK-positive histiocytosis is confirmed, chemotherapy and anti-ALK therapy should be considered, but patients should be alerted to a risk of fatal complications." (PMID 35359354, 2022). "We conclude that ALK-positive histiocytosis can involve the central nervous system and disseminate intracranially." (PMID 35359354, 2022). "In this study, we reported the case of a one-year-and-four-month-old boy who was diagnosed with ALK-positive histiocytosis involving the suprasellar region following clinicopathological, molecular, and next-generation sequencing (NGS) examinations." (PMID 35614430, 2022). "In recent years, ALK-positive histiocytosis, a rare type of histiocytosis, has occasionally been reported." (PMID 35359354, 2022). "Since then, they have reported 10 cases of ALK-positive histiocytosis, including one affecting the cavernous sinus." (PMID 35614430, 2022). "In the current study, enhancement at T1-weighted with intracranial dissemination is characteristic of the ALK-positive histiocytosis." (PMID 35359354, 2022). "ALK-positive histiocytosis should be considered for the differential diagnosis of suprasellar lesions." (PMID 35359354, 2022). "Although the prognosis of ALK-positive histiocytosis is generally good according to the literature, the child in this study died of intracranial infection despite receiving surgery, chemotherapy, anti-ALK, and anti-infective therapy." (PMID 35359354, 2022). "Once the diagnosis of ALK-positive histiocytosis has been established, chemotherapy and anti-ALK therapy are generally applied." (PMID 35359354, 2022).
Histiocytosis (continued). "Among the histiocytic disorders, anaplastic lymphoma kinase (ALK)-positive histiocytosis emerged in 2008." (PMID 35614430, 2022). "Usually, ALK-positive histiocytosis is a benign disease that can be controlled with regular therapy, including surgery, chemotherapy, and anti-ALK therapy." (PMID 35359354, 2022). "ALK-positive histiocytosis is an emerging histiocytic entity that can involve a single organ or multiple organs." (PMID 35982724, 2022). "Here, we report a case of a 3-year-old boy with ALK-positive histiocytosis with systemic masses that was identified to harbor KIF5B-ALK gene fusion." (PMID 35982724, 2022). "AS ALK-positive histiocytosis can spread throughout the multiple systems, it can also disseminate intracranially." (PMID 35359354, 2022). "In the present case, it was necessary to differentiate ALK-positive histiocytosis from other types of histiocytosis." (PMID 35359354, 2022). "Literature search results on the clinical features and outcomes of ALK-positive histiocytosis involving the CNS." (PMID 35359354, 2022). "ALK-positive histiocytosis furthermore converges on the MAPK pathway, which is one of the signaling pathways mediating ALK activation." (PMID 35732831, 2022). "Several patients with ALK-positive histiocytosis have been benefit from crizotinib and alectinib as well." (PMID 35359354, 2022). "We presented a case of ALK-positive histiocytosis involving the suprasellar region of a one-year-and-four-month-old boy." (PMID 35614430, 2022). "Herein, we report a case of ALK-positive histiocytosis invading the respiratory and central nervous systems and report the results of dynamic and detailed follow-up of tumor changes." (PMID 35359354, 2022). "The child underwent partial resection of the suprasellar lesion, and a diagnosis of ALK-positive histiocytosis was made histologically." (PMID 35359354, 2022). "Through clinical, neuropathological, and genomic analyses, the patient was diagnosed with ALK-positive histiocytosis." (PMID 35614430, 2022). "According to a literature review of PubMed using keyword of ALK-positive histiocytosis, 10 cases of ALK-positive histiocytosis invading the CNS have been reported, and lesions located in the frontal lobe are more commonly reported." (PMID 35359354, 2022). "Similar to RDD, ALK-positive histiocytosis shows emperipolesis and stains for histiocytic markers (CD168, CD63, CD4, CD14)." (PMID 36358690, 2022). "In contrast to ALK-positive histiocytosis, the histiocytic sarcoma showed nuclear atypia and high mitotic activity with atypical mitoses." (PMID 34036223, 2021). "In this article, we report a case of ALK-positive histiocytosis localized to the sensory nerve root of a 27-year-old man who presented with neurologic symptoms manifesting mainly as progressive lower limb weakness." (PMID 33973641, 2021). "The most common histology was IMT (n = 3), followed by ALK-positive histiocytosis (n = 1), histiocytic sarcoma (n = 1), osteosarcoma (n = 1), and parotid adenocarcinoma (n = 1)." (PMID 34036223, 2021). "In conclusion, we presented the case of a 27-year-old male who had ALK-positive histiocytosis involving the sensory nerve root in the filum terminale." (PMID 33973641, 2021). "ALK-positive histiocytosis is a relatively new histiocytic proliferation disease with a characteristic gene translocation involving fusion of the ALK gene with different partners, mostly KIF5B." (PMID 33973641, 2021). "Clinical, pathological and molecular features of ALK positive histiocytosis and other histiocytic entities." (PMID 33973641, 2021). "ALK-positive histiocytosis is a recently described distinct clinicopathologic entity." (PMID 41635628, 2026). "Positron emission tomography-computed tomography (PET-CT) subsequently revealed mediastinal space-occupying lesions, multiple hypermetabolic lesions in the liver, kidney, mesentery, and bones, as well as metabolically active systemic lymph nodes, findings consistent with ALK-positive histiocytosis." (PMID 42136678, 2026).
Histiocytosis (continued). "In addition, this study systematically summarizes, for the first time, the age, sex, lesion distribution, fusion genes, treatment strategies, and prognosis of all previously reported pediatric cases of ALK-positive histiocytosis." (PMID 42136678, 2026). "We identified a rare case of ALK-positive histiocytosis with fusion of the ALK gene with TFG." (PMID 40700600, 2025). "In summary, we present a rare case of ALK-positive histiocytosis with unusual DCTN1 fusion." (PMID 40361876, 2025). "Thus, we recommend professionals to perform FISH and—if available—NGS with ALK gene coverage on histiocytosis samples, where ALK immunopositivity is present." (PMID 40361876, 2025). "Notably, some cases of histiocytosis with ALK gene rearrangement have been reported as ECD, JXG, atypical juvenile histiocytosis, or histiocytosis not otherwise specified." (PMID 40700600, 2025). "ALK-positive histiocytosis is a rare subtype of histiocytic neoplasm that was first described in 2008 in three neonates and is now included as a new entity in the fifth edition of the World Health Organization Classification of Haematolymphoid Tumors: Myeloid and Histiocytic/Dendritic Neoplasms." (PMID 40700600, 2025). "We report a very rare case of ALK-positive histiocytosis with TFG-ALK fusion with CR to alectinib." (PMID 40700600, 2025). "Other mutations such as ALK, CSFIR, RET also give rise to lesions in histiocytosis." (PMID 38376733, 2025). "This classification was updated in 2022 under histiocyte/macrophage neoplasms to add anaplastic lymphoma kinase (ALK)-related histiocytosis and histiocytic sarcoma, besides moving LCH to be included in the distinct category "Langerhans cell neoplasms" that also includes Langerhans cell sarcoma." (PMID 39881909, 2024). "We reported a case of ALK-positive histiocytosis with multisystem involvement." (PMID 38463230, 2024). "Touton-type giant cells have been found in ALK-positive histiocytosis, which could lead to a misdiagnosis of malignant GCTB." (PMID 38476985, 2024). "Thus, RDD joins histiocytic sarcoma (HS), Erdheim-Chester disease (ECD), juvenile xanthogranuloma (JXG), and the newly described ALK + histiocytosis in this category." (PMID 39592527, 2024). "The COL1A2-ALK fusion has been found in ALK-positive histiocytosis." (PMID 38476985, 2024). "ALK-positive Histiocytosis (ALK-HSs) is a rare proliferative disease of histiocytes." (PMID 38706599, 2024). "FISH confirmed ALK gene fusion, diagnosing ALK-positive histiocytosis (APH)." (PMID 39867882, 2024). "Moreover, a therapeutic potential of ALK inhibitors in histiocytosis is supported by a limited number of observations that warrant further investigation." (PMID 38339401, 2024). "The therapeutic potential of ALK inhibition in histiocytosis warrants further investigation." (PMID 38339401, 2024). "RDD may sometimes be confused with ALK-positive histiocytosis, but immunohistochemical staining and molecular detection can be used to differentiate between them." (PMID 36915094, 2023). "Moreover, ALK-positive histiocytosis has been considered a distinct histiocytic neoplasm in the 5th WHO classification and International Consensus Classification." (PMID 36915094, 2023). "Moreover, ALK-positive histiocytosis with EML4-ALK fusion in the lungs of a 52-year-old woman and a 17-year-old boy has also been reported." (PMID 36915094, 2023). "In addition, one particular case has been described, in which bone marrow biopsy showed concomitant chronic lymphocytic leukemia/small lymphocytic lymphoma and ALK-positive histiocytosis." (PMID 36915094, 2023). "In addition, other studies have reported favorable outcomes of ALK inhibitors with ALK-positive histiocytosis." (PMID 36915094, 2023). "We identified 19 cases of ALK-positive histiocytosis with CNS involvement in the literature." (PMID 36915094, 2023).
Histiocytosis (continued). "Anaplastic lymphoma kinase (ALK)-positive histiocytosis is a rare type of histiocytosis that could affect multiple systems in children and adults." (PMID 35359354, 2022). "ALK-positive histiocytosis in the central nervous system (CNS) has been rarely reported." (PMID 35614430, 2022). "Multiple organs were affected by the ALK-positive histiocytosis." (PMID 35614430, 2022). "Touton-type multinucleated giant cells have been found in ALK-positive histiocytosis." (PMID 35359354, 2022). "It appears that disseminated growth is a characteristic of ALK-positive histiocytosis." (PMID 35359354, 2022). "Therefore, ALK-positive histiocytosis was suspected and confirmatory molecular testing for the presence of ALK gene translocation, which was performed at an outside facility, showed the presence of KIF5B-ALK gene fusion by RT-PCR, confirming the diagnosis." (PMID 33973641, 2021). "ALK-positive histiocytosis is a relatively recent entity among the histiocytic disorders." (PMID 33973641, 2021). "Whether this condition truly represents a variant of juvenile xanthogranuloma or a continuation of the spectrum of ALK-positive histiocytosis is debatable, although we favor the latter." (PMID 33973641, 2021). "Except for ALCL, several hematopoietic neoplasms have been reported to have the following ALK fusion partners: CLTC, NPM1, SEC31A, SQSTM1, RANBP2, and EML4 in ALK-positive large B-cell lymphoma; TPM3 in ALK-positive histiocytosis; and RANBP2 in myeloid leukemia." (PMID 30941048, 2019). "The association between case 6 in the present study and ALK-positive histiocytosis is unknown as the pathology was not rereviewed." (PMID 38476985, 2024). "Finally, the patient was diagnosed with ALK-positive histiocytosis." (PMID 35359354, 2022). "The presence of the blood–brain barrier may affect the action of ALK-tyrosine kinase inhibitor in the CNS, but there is insufficient evidence to support the hypothesis that the efficacy of chemotherapy and anti-ALK therapy is greater for ALK-positive histiocytosis in the lung than in the cerebrum." (PMID 35359354, 2022). "ALK-positive histiocytosis may involve the central nervous system and disseminate intracranially." (PMID 35359354, 2022). "ALK-positive histiocytosis can occur in both children and adults, and may involve multiple systems." (PMID 35359354, 2022). "However, it may arise in cases of ALK-positive histiocytosis with diffuse cytoplasmic positivity of S-100 protein, especially when emperipolesis is also present." (PMID 35359354, 2022). "Rare ALK fusions have also been described, although the WHO classification now recognizes an ALK-positive histiocytosis as a distinct entity." (PMID 40235191, 2025). "It is also worth noting that ALK‐positive histiocytosis is the first molecularly defined histiocytic neoplasm, as it is characterized by ALK rearrangements, such as the KIF5B::ALK fusion." (PMID 40938275, 2025). "Other signaling pathways for which we have specific inhibitors (AKT/mTOR, ALK, and CSF1R) now pave the way for targeted therapies rather than conventional chemotherapy regimens in adult clonal histiocytosis." (PMID 37809108, 2023). "The discovery of additional mutations in LCH including A-RAF, N/KRAS, PIK3CA, and gene fusions involving B-RAF, ALK, and NTRK enrich the variegate landscape of the histiocytosis and further complicate the therapeutic choice." (PMID 34944576, 2021). "It is worth mentioning that this classification does not include ALK-positive histiocytosis as a separate entity among histiocytosis entities." (PMID 40361876, 2025). "Unlike Touton giant cells which are common in JX, ALK + histiocytosis, and ECD, they are not typical of RDD." (PMID 39592527, 2024). "The VRK2-ALK and DCTN1-ALK fusion thus may lead to activation of ALK gene driving the tumorigenesis in the ALK-positive histiocytosis." (PMID 36915094, 2023). "In conclusion, four cases of multisystem ALK-positive histiocytosis without hematopoietic involvement are reported." (PMID 36915094, 2023).